FGFR3 (fibroblast growth factor receptor 3)
Diseases named in the same sentence as FGFR3 in open-access papers (continued):
Sharing a sentence is not in itself a finding about the gene and the disease.
achondroplasia (continued). "Fibroblast growth factor receptor 3 (FGFR3) is a direct target of SHOX, and FGFR3 mutations cause achondroplasia, a condition treatable with C-type natriuretic peptide (CNP) analogues." (PMID 42077444, 2026). "Vosoritide is a synthetic analog CNP that counteracts constitutively activated FGFR3 and the downstream MAPK pathway activity that causes achondroplasia." (PMID 41340868, 2025). "Vosoritide (VOXZOGO®), a C-type natriuretic peptide analog, is the first targeted therapy approved for achondroplasia and acts by antagonizing FGFR3 signaling to promote bone growth." (PMID 40821249, 2025). "In 1994, one recurrent mutation in FGFR3 was identified as causing achondroplasia (ACH)." (PMID 40178985, 2025). "Achondroplasia (ACH) and hypochondroplasia (HCH) are among the most common forms of skeletal dysplasia, both caused by gain-of-function pathogenic variants in the fibroblast growth factor receptor 3 (FGFR3) gene, which lead to increased FGFR3 signaling." (PMID 41184854, 2025). "The FGFR3 variations in Cases 9, 24, and 25 were recurrent and shown to be causative for achondroplasia (ACH, #100800), thanatophoric dysplasia type I (TD I, #187600), and ACH (Foldynova‐Trantirkova, Wilcox, and Krejci 2012), respectively." (PMID 39831619, 2025). "Vosoritide is a synthetic analog of C-type natriuretic peptide (CNP) that works to counteract constitutively activated FGFR3 and the downstream MAPK pathway activity that causes achondroplasia." (PMID 41340868, 2025). "CNP analogs, such as vosoritide, which is currently approved for achondroplasia, have shown efficacy in promoting linear growth by antagonizing FGFR3-mediated inhibition." (PMID 40723048, 2025). "Achondroplasia (ACH), is the prevailing type of genetic dwarfism in humans, caused by mutations in fibroblast growth factor receptor 3 (FGFR3) that are inherited in an autosomal dominant manner." (PMID 40256430, 2025). "Among these genes, it is worth mentioning the fibroblast growth factor receptor 3 (FGFR3), as mutations in this gene are known to cause dwarfism and achondroplasia in humans." (PMID 40607659, 2025). "TYRA-300, an FGFR3-selective kinase inhibitor, increases bone growth in mouse models of achondroplasia and hypochondroplasia." (PMID 40178985, 2025). "De novo variants in FGFR3 (OMIM: *134934) were the most commonly identified, found in 30 patients with achondroplasia (OMIM: #100800) and hypochondroplasia (OMIM: #146000)." (PMID 40130161, 2025). "The second most common diagnostic category is FGFR3-related chondrodysplasias, with six diagnosed cases: five thanatophoric dysplasia type 1 (TD1) and one achondroplasia." (PMID 40500351, 2025). "Achondroplasia (ACH) is the most common skeletal dysplasia characterized by short-limbed short stature with rhizomelia, due to a mutation in the FGFR3 gene." (PMID 40364888, 2025). "Achondroplasia (ACH), a rare skeletal dysplasia caused by mutations in the fibroblast growth factor receptor 3 (FGFR3) gene with a prevalence of 1 in 25,000, is observed in both males and females equally." (PMID 39338043, 2024). "There are other treatments in clinical development that target the FGFR3/CNP pathway for treatment of achondroplasia, including TransCon CNP (Ascendis Pharma, Copenhagen, Denmark) and infigratinib (Truseltiq; QED Therapeutics, Brisbane, CA)." (PMID 38078681, 2024). "If the patient has an established diagnosis but testing results cannot be located, a new targeted FGFR3 test for achondroplasia should be obtained." (PMID 39062238, 2024). "Frequently identified causal mutations in osteochondrodysplasia arise in the coding sequences of the FGFR3 gene: c.1138G>A and c.1138G>C in achondroplasia and c.1620C>A and c.1620C>G in hypochondroplasia." (PMID 38397214, 2024).
achondroplasia (continued). "Although bone regeneration in young patients with FGFR3-related skeletal dysplasias, including achondroplasia and hypochondroplasia, is usually enhanced, aging and post-menopause would lead to poor bone healing in addition to low BMD in these patients." (PMID 36927417, 2023). "Achondroplasia and hypochondroplasia are part of the Fibroblast Growth Factor Receptor 3 (FGFR3) family of diagnoses." (PMID 37675393, 2023). "Achondroplasia is the most frequent FGFR3-related chondrodysplasia, leading to rhizomelic dwarfism, craniofacial anomalies, stenosis of the foramen magnum, and sleep apnea." (PMID 37072824, 2023). "An activating point mutation in FGFR3 (FGFR3G308R) is associated with the most common genetic form of human dwarfism, achondroplasia." (PMID 35887171, 2022). "Lastly, C-type natriuretic peptide inhibits aberrantly activated FGFR3-mediated MAPK signaling in achondroplasia, thereby restoring longitudinal growth of endochondral bones." (PMID 35887171, 2022). "In achondroplasia, the normal reciprocal antagonism between FGFR3 (inhibiting endochondral bone growth) and CNP signaling (stimulating bone growth) is disregarded by a gain of function mutation in FGR3." (PMID 35682595, 2022). "Meclozine has been developed as an inhibitor of fibroblast growth factor receptor 3 (FGFR3) to treat achondroplasia (ACH)." (PMID 35118060, 2021). "As supported by the comparison of height trajectories to that of average stature children, the achondroplasia-specific FGFR3 mutation influence on linear growth is, of course, greater than any environmental or ethnic factor that could be derived from other studies of linear growth in achondroplasia." (PMID 34949201, 2021). "Achondroplasia (ACH), the most common form of dwarfism, is due to a gain-of-function mutation in the fibroblast growth factor receptor type 3 (FGFR3) gene." (PMID 33986191, 2021). "It has been demonstrated that specific RAS/MAPK signaling inhibition in an achondroplasia murine model (Fgfr3 Y367C/+) leads to a significant recovery of bone growth." (PMID 34149626, 2021). "This can be exemplified by activating FGFR3-K650E/M mutation, causing thanatophoric dysplasia type II and SADDAN (severe achondroplasia with developmental delay and acanthosis nigricans), respectively." (PMID 34207779, 2021). "Achondroplasia (ACH), the most common form of dwarfism, is caused by a missense mutation in the gene coding for fibroblast growth factor receptor 3 (FGFR3)." (PMID 33737326, 2021). "The ideal drug for achondroplasia should be small in size, to readily penetrate the growth plate, be specific for FGFR3 and effectively inhibit its signaling pathway." (PMID 34070375, 2021). "Among patients with the FGFR3-related molecular diagnoses, four patients with clinical suspicion of achondroplasia (including one fetal case) received a confirmed molecular diagnosis of the FGFR3 NP_000133.1:Gly380Arg variant." (PMID 34627339, 2021). "Mutations in the gene encoding fibroblast growth factor receptor 3 (FGFR3) are responsible for the phenotypes of several skeletal chondrodysplasias, including achondroplasia, the most common form of short limb and short stature." (PMID 33370388, 2020). "For example, mutations in ACVR1, FGFR3, PTHrP, and GLI2 genes result in fibrodysplasia ossificans progressive (FOP), achondroplasia (ACH), brachydactyly type E2, and Culler–Jones syndrome, respectively." (PMID 32079226, 2020). "Recifercept is a modified soluble recombinant human FGFR3 designed to be a decoy protein, competing for ligands of the FGFR3-G380R receptor responsible for achondroplasia." (PMID 33370388, 2020). "Comparatively, activating mutations of the FGFR3, one of the receptors for FGF4, are responsible for some of the most common causes of disproportionate dwarfism in humans including achondroplasia." (PMID 32793650, 2020).
achondroplasia (continued). "In low doses, this re-purposed drug demonstrates its inhibitory effect on FGFR3 signalling, thereby increasing chondrocyte proliferation and differentiation, and rescuing the short-limbed phenotype in a transgenic mouse model of achondroplasia." (PMID 32144686, 2020). "On the other hand circulating NT-proCNP levels are elevated in patients with achondroplasia, which suggests that FGFR-3 induced suppression of CNP/NPR-B signaling would increase Nppc expression." (PMID 33002060, 2020). "Activation of FGFR3 can also lead to achondroplasia, which results in a more extreme disproportionate short stature than XLH." (PMID 30808384, 2019). "Aside from this, a missense mutation leading to a constantly active FGF receptor 3 (FGFR3), the authentic receptor for FGF18, was discovered to be the cause of the genetic short limb dwarfism, achondroplasia (ACH)." (PMID 31614494, 2019). "Cranial malformations arise in a range of diseases that involve activation of FGF23 receptors, including osteoglophonic dysplasia (OGD) (FGFR1,), Crouzon and Apert syndromes (FGFR2,) and achondroplasia (FGFR3,)." (PMID 30808384, 2019). "In order to better manage obesity, it is necessary to considerer the potential nutrigenetics effect of the FGFR3 gene in the context of achondroplasia." (PMID 31727132, 2019). "Achondroplasia remains one of the rare cases proving a possible relationship between FGFR3 signaling and the development of metabolic alterations." (PMID 31727132, 2019). "Meclizine (an over the counter medication for motion sickness) improves long bone growth in a mouse model of achondroplasia, apparently through inhibition of activity of downstream effectors of FGFR3." (PMID 30606190, 2019). "The Ach model showed increased Fgfr3 expression in the proliferative zone extending to the hypertrophic layer in the growth plate compared to WT mice, which is consistent with other achondroplasia models." (PMID 29323153, 2018). "Mutations in FGFR3 cause other disorders such as hypochondroplasia, thanatophoric dysplasia and SADDAN (severe achondroplasia with developmental delay and acanthosis nigricans)." (PMID 29972438, 2018). "BMN 111 has previously been shown to partially correct the long bone growth plate defect in 7- or 21-day old Fgfr3 mouse models of achondroplasia." (PMID 30048539, 2018). "Very interestingly, in achondroplasia mice treated with soluble FGFR3 during the growth period (from D3 to D22), the development of these metabolic deregulations was prevented in adult animals (between 4 and 14 weeks of age)." (PMID 29652901, 2018). "Activation of the C-type natriuretic peptide (CNP) signaling pathway, which antagonizes FGFR3 signaling in chondrocytes, is being evaluated as a therapeutic for achondroplasia." (PMID 27056048, 2016). "It facilitated differentiation of chondrocytes by attenuating abnormally activated FGFR3 signaling in achondroplasia." (PMID 26921194, 2016). "Another valuable therapeutic candidate in the treatment of achondroplasia is CNP that works as an antagonist to FGFR3 signal." (PMID 25530967, 2014). "For instance, while FGFR3 is expressed in all cell types, the achondroplasia phenotype is restricted primarily to the skeletal system." (PMID 23056398, 2012). "In all cases the achondroplasia FGFR3 gene defect dominated the clinical picture, even prenatally, and the Klinefelter syndrome is not able to counter the achondroplasia’s effects on height." (PMID 22747519, 2012). "We observe identical behavior of the two achondroplasia mutants in these experiments, a finding which supports a direct link between the severity of dwarfism phenotypes and the level and mechanism of FGFR3 over-activation." (PMID 22529939, 2012). "The EXT1 and EXT2 genes (30 cases) for multiple cartilaginous exostoses, the FBN1 gene for Marfan syndrome (24 cases), and the FGFR3 gene for achondroplasia (22 cases) were most frequently reported in Chinese biomedical literature from the CBM database." (PMID 22913777, 2012).
achondroplasia (continued). "Achondroplasia (ACH) is the most frequent form of short-limbed dwarfism, caused by mutations in the FGFR3 gene." (PMID 19838370, 2009). "Mutations that affect the growth of long bones resulting in syndromes such as Achondroplasia (Ach) and Thanatophoric dysplasia (TD) are mainly localized to FGFR3." (PMID 16504022, 2006). "How FGFR3 overactivation in achondroplasia disrupts Meckel's and condylar cartilages is largely unknown." (PMID 41954527, 2026). "Development of pharmacologic disease-modifying therapies for potential use in the treatment of achondroplasia has relied on mechanistic approaches that target the FGFR3 pathway directly or the C-natriuretic peptide pathway, which regulates longitudinal bone growth." (PMID 40016839, 2025). "This pathway is downstream of FGFR3 and is activated in hypochondroplasia and achondroplasia." (PMID 38813446, 2024). "Achondroplasia (ACH; MIM #100,800), caused by a heterozygous gain of function pathogenic variant in the fibroblast growth factor receptor 3 gene (FGFR3; MIM*134,934), is the most prevalent and most readily identifiable cause of disproportionate short stature that is compatible with life." (PMID 38879704, 2024). "Conditions such as achondroplasia and Apert syndrome, are known to be induced by single point mutations in fibroblast growth factor receptors (FGFRs): FGFR2, in the case of Apert syndrome, and FGFR3, in the case of achondroplasia." (PMID 37568254, 2023). "Vosoritide was FDA approved in 2021, as an analog of C-type natriuretic peptide, capable of binding to the natriuretic peptide receptor type 2 and interrupting downstream signaling of the constitutively active FGFR3-mediated MAPK pathway present in achondroplasia." (PMID 36304528, 2022). "By targeting FGFR3 signaling, vosoritide ameliorates the clinical phenotype of achondroplasia." (PMID 36304528, 2022). "Achondroplasia (ACH) is one of the most prevalent genetic forms of short-limbed skeletal dysplasia, caused by gain-of-function mutations in the receptor tyrosine kinase FGFR3." (PMID 35710503, 2022). "Furthermore, meclozine, an anti-histamine used to treat motion sickness, inhibits FGFR3 activity in chondrocyte cell lines and in a mouse model of achondroplasia, where it rescued the skeletal defects." (PMID 35887171, 2022). "Prenatal genetic testing was not possible until the pathologic variant in FGFR3 causing achondroplasia was identified in 1994.4,5,33,34 Technological advancement in amniocentesis and chorionic villus sampling also were needed to execute molecular studies." (PMID 34006999, 2021). "The developmental mechanisms of midfacial hypoplasia and foramen magnum stenosis in achondroplasia are related to FGFR3 and mitogen-activated protein kinase (MAPK) signaling in chondrocytes, which regulates synchondrosis closure, osteoblast differentiation, and bone formation." (PMID 31120905, 2019). "We have thus decided to study obesity in patients and to use the mouse model to evaluate if soluble FGFR3 therapy, an innovative treatment approach for achondroplasia, could also impact the development of this significant complication." (PMID 29652901, 2018). "The presence of recurrent de novo missense mutation associated with a specific disease is most commonly explained by specific dominant negative or gain-of-function effects, such as those in FGFR3 causing achondroplasia." (PMID 30107533, 2018). "We previously reported that overexpression of CNP in chondrocytes counteracts dwarfism of an achondroplasia model mouse with activated FGFR-3 in the cartilage, and exhibited that inhibition of the MAPK/ERK pathway is one of the mechanism of an antagonistic effect of CNP to FGFR-3 signaling." (PMID 30235256, 2018). "Introduction of those constitutively active GC-B mutants may mimic the overexpressing CNP-induced GC-B activation in chondrocytes and is likely to suppress FGFR3-dependent achondroplasia." (PMID 23586811, 2013).
achondroplasia (continued). "A study by Bellus at al compared the ligand-independent phosphorylation of FGFR3 mutants implicated in (i) thanatophoric dysplasia type 2 (TD2), (ii) severe achondroplasia with developmental delay and acanthosis nigricans (SADDAN), and (iii) hypochondroplasia (HCH)." (PMID 22529939, 2012). "The p.G380R substitution in the transmembrane domain of the FGFR3 protein, as identified in this case, is present in >98% of achondroplasia patients, and may either have arisen sporadically or be due to germline mosaicism." (PMID 22747519, 2012). "The disease associations in OMIM for these genes also revealed that 38% were hereditary cancer predisposition syndromes (e.g., VHL associated with von Hippel-Lindau syndrome) and 62% were not known to include cancer as a predominant feature (e.g., FGFR3 associated with Achondroplasia)." (PMID 39761285, 2025). "Achondroplasia (ACH) is a skeletal dysplasia characterized by disproportionate short stature, resulting from the constitutive activation of fibroblast growth factor receptor 3 (FGFR3), with an estimated global prevalence of over 250,000 individuals." (PMID 40831806, 2025). "Achondroplasia (ACH) and hypochondroplasia (HCH), the two most common types of dwarfism, are each caused by FGFR3 gain-of-function mutations that result in increased FGFR3 signaling, which disrupts chondrogenesis and osteogenesis, resulting in disproportionately shortened long bones." (PMID 40178985, 2025). "Achondroplasia (ACH) and hypochondroplasia (HCH) are among the most common forms of skeletal dysplasia, caused by gain-of-function variants in the FGFR3 gene, leading to disproportionate short stature." (PMID 41184854, 2025). "These strong evidences of FGFR3 implications in the RAS/MAPK signaling pathway along with our in silico results of the interactome, let us suggest that FGFR3 disorders (thanatophoric dysplasia, achondroplasia, and hypochondroplasia) may be included among the RASopathies." (PMID 34229750, 2021). "With such a result, hypochondroplasia may have arisen either because of a mutation in FGFR3 or at some other locus, but making that distinction is not nearly so important as making the distinction between achondroplasia and hypochondroplasia." (PMID 30606190, 2019). "The phenotypes of CNP-KO and activated fibroblast growth factor receptor 3 achondroplasia-phenotype (Fgfr3ach) mice were similar to those in patients with achondroplasia, and the skull morphologies and narrow foramen magnum also resemble those in patients with achondroplasia." (PMID 31120905, 2019). "One successful example is the pathogenic elucidation of FGFR3 signaling in achondroplasia (ACH) that led to an effective therapeutic regimen via antagonizing FGFR3 downstream signaling." (PMID 30024379, 2018). "Although considered to be the most frequently mutated nucleotide in the germline with a birth prevalence of about 1:30,000, we did not detect the FGFR3 c.1138G > A or c.1138G > C achondroplasia-associated mutations due to exclusion of this region because of insufficient coverage (less than 5000×)." (PMID 30355600, 2018). "Our findings agree with the world-wide sharing of p.G380R mutation among achondroplasia subjects and extend the body of evidence that supports the role of FGFR3 gene in ACH." (PMID 28679403, 2017). "Additionally, germline mutations at the paralogous position have been identified in FGFR3 associated with three different skeletal syndromes – TDII (p.K650E), severe achondroplasia with developmental delay and aconthosis nigricans (SADDAN) syndrome, and TDI (both due to p.K650M)." (PMID 23527311, 2013). "The importance of FGFR3 in early bone development was established from the association of point mutations in FGFR3 with dominant chondrodysplasias ranging in severity from mild (hypochondroplasia [HCH] and achondroplasia [ACH]) to severe (thanatophoric dysplasia [TD])." (PMID 19898608, 2009).